DNAH6 (dynein axonemal heavy chain 6)
Description:
Force generating protein of respiratory cilia. Produces force towards the minus ends of microtubules. Dynein has ATPase activity; the force-producing power stroke is thought to occur on release of ADP (By similarity).
Synonyms: DNAHC6; DNHL1; HL2; HL-2; FLJ37357
Tractability: Small molecule: a structure with a bound ligand is known. Antibody: the Human Protein Atlas places it where antibodies can reach. PROTAC: ubiquitination databases record sites on it.
Gene: Protein-coding gene on chromosome 2 (84,516,455 to 84,819,589, forward strand). Ensembl gene ENSG00000115423.
Subcellular location: Cytoplasm, cytoskeleton, cilium axoneme; Cell projection, cilium, flagellum
Subcellular location (Human Protein Atlas): Basal body; Centriolar satellite; Connecting piece; Mid piece; Plasma membrane; Calyx; Primary cilium tip
Gene Ontology:
Molecular function: dynein intermediate chain binding; dynein light intermediate chain binding; minus-end-directed microtubule motor activity; ATP binding
Biological process: cilium movement involved in cell motility; microtubule-based movement
Cellular component: sperm flagellum; 9+2 motile cilium; dynein complex; axoneme; motile cilium
Genetic constraint (gnomAD): Loss-of-function variants: 261 observed, 385.33 expected, observed/expected ratio (o/e) 0.68, 90% interval 0.61 to 0.75. The upper end of that interval is the gene's LOEUF score, 0.75, which puts it in group 3 of 6, group 1 being the genes least tolerant of losing a copy. Missense variants: 3,807 observed, 4,431.3 expected, observed/expected ratio (o/e) 0.86, 90% interval 0.84 to 0.88. Synonymous variants: 1,395 observed, 1,522.1 expected, observed/expected ratio (o/e) 0.92, 90% interval 0.88 to 0.96.
Gene-disease validity (ClinGen):
ClinGen rates the evidence that DNAH6 causes each of these diseases.
spermatogenic failure (autosomal recessive): Strong. A male infertility characterized by dirsuption of the process of sperm development from diploid cells into mature haploid spermatozoa.
primary ciliary dyskinesia (autosomal recessive): Disputed. A rare, genetically heterogeneous, primarily respiratory disorder characterized by chronic upper and lower respiratory tract disease.
Homologues: Orthologues: chimpanzee DNAH6 (99% identical), macaque DNAH6 (98% identical), pig DNAH6 (91% identical), dog DNAH6 (91% identical), rabbit DNAH6 (91% identical), guinea pig DNAH6 (89% identical), rat Dnah6 (89% identical), mouse Dnah6 (88% identical), tropical clawed frog dnah6 (76% identical), zebrafish dnah6 (70% identical), Drosophila melanogaster Dhc16F (44% identical). Paralogues in human: DNAH14 (36% identical), DNAH1 (35% identical), DNAH7 (35% identical), DNAH3 (35% identical), DNAH12 (34% identical), DNAH2 (34% identical), DNAH10 (32% identical), DNAH9 (30% identical), DNAH17 (30% identical), DNAH11 (30% identical), DNAH8 (28% identical), DNAH5 (28% identical), and 3 more.
Diseases named in the same sentence as DNAH6 in open-access papers:
DNAH6 is named in the same sentence as 18 diseases in open-access papers, as found by Europe PMC text mining. Sharing a sentence is not in itself a finding about the gene and the disease. The quoted sentences say what the papers report.
primary ciliary dyskinesia (6 papers, 2016 to 2025). "Mutations in DNAH6 cause primary ciliary dyskinesia and Huntington’s disease, both of which are associated with infertility." (PMID 34199109, 2021). "DNAH6 is an IDA protein component, and defects in it can lead to heterotaxy and primary ciliary dyskinesia." (PMID 40898283, 2025). "Previous studies have shown that dynein axonemal heavy chain 6 (DNAH6) is involved in generating the force required for ciliary beating, and mutations in this gene may cause primary ciliary dyskinesia, non-obstructive azoospermia, or sperm morphological defects." (PMID 32962729, 2020).
male infertility (4 papers, 2022 to 2024). The inability of the male to effect fertilization of an ovum after a specified period of unprotected intercourse. "In humans, loss-of-function mutations in DNAH6 have been implicated in male infertility, such as globozoospermia, acephalic spermatozoa syndrome and azoospermia, and even premature ovarian insufficiency." (PMID 37424858, 2023). "Additional functional analysis of specific DNAH6 mutations would provide further important information about the underlying genetic causes of male infertility, allowing genetic counselors and clinicians to develop personalized treatment plans." (PMID 37424858, 2023). "Meanwhile, the ICSI outcomes in male infertility caused by DNAH6 variants may depend on the specific mutation or be controversial." (PMID 39503742, 2024). "Furthermore, mutations in DNAH6 were shown to be associated with spermatogenic abnormalities and male infertility." (PMID 34190021, 2022). "We have also identified putatively causal variants in seven genes validated as aetiological factors of male infertility, such as SPAG17, REC114, TERB1, DNAH6, ADGRG2, MAMLD1, and USP26." (PMID 39678461, 2024).
Globozoospermia (2 papers, 2020 to 2024). Any structural anomaly of the acrosome resulting in a round sperm head. "In addition, Li and colleagues reported the case of a patient with globozoospermia presenting a compound heterozygous mutation of the DNAH6 gene and suggesting DNAH6 as a novel candidate gene for globozoospermia." (PMID 38790229, 2024). "A subset of genetic mutations, such as DNAH6, SPATA16, DPY19L2, PICK1, and CCIN related to globozoospermia, have been reported in the past few years." (PMID 32582379, 2020).
infertile (2 papers, 2021 to 2023). "Furthermore, intracytoplasmic sperm injection could achieve successful fertilization in infertile men with DNAH6 mutations." (PMID 37424858, 2023).
acephalic spermatozoa syndrome (1 paper, 2021). "BRDT, DNAH6, CEP112, and HOOK1 have also been reported to be associated with acephalic spermatozoa syndrome." (PMID 34422805, 2021).
asthenozoospermia (1 paper, 2023). "After screening, only one novel homozygous frameshift variant (NM_001370.2: exon 17: c.2823dupT, p.Val942Cysfs*21) in DNAH6, known to cause asthenozoospermia, fulfilled these criteria." (PMID 37424858, 2023).
asthma (1 paper, 2024). "Additional genetic factors, such as genetic variations in some PCD-causing genes (DNAH14, DNAAF3, DNAH6, DNAH5, KIFC2, KIF3A), are associated with the increased risk of asthma development." (PMID 39337527, 2024).
cystic fibrosis (1 paper, 2024). Autosomal recessive disorder caused by pathogenic variants in the CFTR gene (cystic fibrosis transmembrane conductance regulator), which encodes a chloride and bicarbonate channel expressed in epithelial cells, and follow the diagnosis criteria. "Variants in genes underlying the development or function of cilia, such as DNAH14 and DNAAF3, were associated with poor lung function in cystic fibrosis, whereas variants in DNAH6 were associated with preserved lung function in cystic fibrosis." (PMID 39337527, 2024).
Dextrocardia (1 paper, 2021). The heart is located in the right hand sided hemithorax. "It is worth noting that DNAH1:p.Tyr3688Cys (as an example) was found in heterozygous state in a child with dextrocardia; the only other variant reported in the genes of interest in this patient was DNAH6:p.Ile213Val (Condel: 0.00)." (PMID 34768622, 2021).
lung carcinoma (1 paper, 2022). "Dynein axonemal heavy chain 6 (DNAH6) belongs to the dynein family, whose members encode large proteins that constitute the microtubule-associated motor protein complex; it has recently been related to smoking-associated lung cancer." (PMID 34870316, 2022).
melanoma (1 paper, 2025). A malignant, usually aggressive tumor composed of atypical, neoplastic melanocytes. "Additionally, the EPDnew-validated promoter of Dnah6, previously implicated in ICB response in human melanoma, was found to be hypermethylated in the red clade." (PMID 40950124, 2025).
periodontitis (1 paper, 2025). An acute or chronic inflammatory process that affects the tissues that surround and support the teeth. "A recent study showed that DNAH6 inhibition affects osteoblastic differentiation in Porphyromonas gingivalis-induced periodontitis." (PMID 40004451, 2025).
infection (1 paper, 2023). The state of being infected such as from the introduction of a foreign agent such as serum, vaccine, antigenic substance or organism. "In contrast, we observed no decrease in expression of ciliated cell markers (Foxj1/Dnah6) in the lungs of the infected FOXJ1-ACE2 transgenic animals, suggesting that infection of these cells with SARS-CoV-2 may result in a very different sequence of events." (PMID 36812267, 2023).
lung (1 paper, 2018). "Nevertheless, we observed that genes such as DNAH6, MUC5B, HELZ2, and KIAA0100 were frequently mutated in three of six lung ACC metastases." (PMID 30301885, 2018).
DNAH6 also shares sentences with these, for which no sentence is quoted: Azoospermia (2 papers); hereditary spastic paraplegia (1); Huntington disease (1); muscular dystrophy (1).